LHX1 (LIM homeobox 1)
Diseases named in the same sentence as LHX1 in open-access papers:
LHX1 is named in the same sentence as 60 diseases in open-access papers, as found by Europe PMC text mining. Sharing a sentence is not in itself a finding about the gene and the disease. The quoted sentences say what the papers report.
MRKH syndrome (7 papers, 2009 to 2024). "The present data also recommend searching for 17q12 hemizygosity and/or mutations in the candidate TCF2 and LHX1 genes, both in type I and type II MRKH syndrome." (PMID 19889212, 2009). "The patient, who carries the LHX1 missense mutation, has a type I MRKH syndrome." (PMID 29527097, 2018). "LHX1, coding for LIM homeobox 1, is also found in the 17q12 area and heterozygote variants are known to cause Müllerian duct abnormalities/Mayer-Rokitansky-Küster-Hauser syndrome." (PMID 29576871, 2018). "The most reported genes implicated in the pathogenesis of MRKH syndrome have been WNT4, LHX1 (LIM homebox protein 1) and HNF1B (hepatocyte nuclear factor-1B)." (PMID 38841305, 2024). "A number of studies aimed to investigate the genetic causes of MRKH syndrome, focusing on CNVs and candidate genes involving TBX6, AMH, LHX1, WNT, and HOX." (PMID 37789575, 2023). "Of those, LHX1, EMX2 and the Hox genes have previously been associated with MRKH syndrome either by sequencing of patient blood or functional in vivo studies with animal models." (PMID 35394036, 2022). "By analysing candidate genes, being located in these aberrations, mutations in genes such as LHX1, RBM8A and TBX6 have been identified as being causative of MRKH syndrome." (PMID 29527097, 2018). "Female Lhx1-null mice lack a uterus and oviducts together with a complete absence of both the epithelium and the mesenchyme of the female reproductive tract, while the ovaries are unaffected, a phenotype strongly resembling MRKH syndrome in humans." (PMID 29527097, 2018). "As reported, array-CGH detected a microdeletion at chromosome 17q12, which encompasses LHX1 and HNF1B genes, in one MRKH affected women of our Italian cohort, so confirming this region as the most frequent chromosomal alteration associated with MRKH syndrome." (PMID 33432050, 2021). "In view of these considerations, our findings confirm LHX1 and HFN1B as strong candidate genes for MRKH syndrome and push towards additional functional studies to better understand their biological role in this syndrome." (PMID 33432050, 2021). "All of these findings suggest a common pathway in MRKH syndrome with WNT9B acting upstream of WNT4 and LHX1." (PMID 29527097, 2018).
breast carcinoma (3 papers, 2017 to 2025). "Similar to our work, the other risk gene LHX1 was also adopted in a recent published prognostic signature of breast cancer." (PMID 40183093, 2025).
clear cell renal cell carcinoma (3 papers, 2017 to 2022). "Additionally, LHX1 was reported as a driver gene of clear cell renal cell carcinoma proliferation, apoptosis, and promoting tumor growth." (PMID 31787845, 2019).
colorectal cancer (3 papers, 2019 to 2025). A primary or metastatic malignant neoplasm that affects the colon or rectum. "The aim of this study was to investigate the effect of sodium butyrate (NaB) as a histone deacetylase inhibitor (HDACi) on the expression of the HDAC8 gene in the colorectal cancer cell line, and the molecular docking of the LHX1 transcription factor with NaB." (PMID 32788915, 2020). "In this study, different effects of SB on LHX1 mRNA expression level were revealed in two distinct human colorectal cancer cell lines." (PMID 31908740, 2019). "The aim of this study was to investigate the effect of Sodium Butyrate (SB), as a histone deacetylase inhibitor, on the expression of LHX1 gene in colorectal cancer cell lines." (PMID 31908740, 2019). "In this study, the expression of LHX1 gene was investigated in untreated and treated colorectal cells and different effects of SB on LHX1 mRNA expression were revealed in two different human colorectal cancer cell lines." (PMID 31908740, 2019). "The effect of SB was examined on LHX1 mRNA expression in HT-29 human colorectal cancer cell line in vitro by incubating the cells in 6.25, 12.5, 25, 50, and 100 mM concentrations of SB for 24 and 48 hr." (PMID 31908740, 2019). "Future studies are needed to evaluate the effect of SB on LHX1 mRNA expression in other human colorectal cancer cell lines as well as other cancer cell lines." (PMID 31908740, 2019). "In this study, the effect of SB on LHX1 as a transcription factor of HDAC8 in colorectal cancer cell lines was investigated." (PMID 31908740, 2019). "Also, the effects of SB on LHX1 mRNA expression in HCT-116 human colorectal cancer cell line were investigated in vitro by incubating the cells in 6.25, 12.5, 25, 50, and 100 mM concentrations of SB for 24 and 48 hr." (PMID 31908740, 2019). "Moreover, the results of this study showed that LHX1 mRNA expression level was significantly different between two human colorectal cancer cell lines (HT-29 and HCT-116) due to SB treatment." (PMID 31908740, 2019).
Ataxia (2 papers, 2017 to 2022). Ataxia refers to impaired coordination of voluntary muscle movement. "Together, the results suggest that inactivation of Lhx1/5 in postnatal PCs leads to nonprogressive ataxia and motor deficits." (PMID 28516904, 2017).
endometrial carcinoma (2 papers, 2020 to 2022). A malignant tumor arising from the epithelium that lines the cavity of the uterine body. "•LHX1 is highly upregulated in the cells and tissues of Uterine Corpus Endometrial Carcinoma (UCEC)." (PMID 36116266, 2022).
epilepsy (2 papers, 2022 to 2025). A brain disorder characterized by episodes of abnormally increased neuronal discharge resulting in transient episodes of sensory or motor neurological dysfunction, or psychic dysfunction. "LHX1, encoding LIM homeobox protein 1, and ACACA, encoding acetyl-CoA carboxylase, have been proposed as potential candidate genes responsible for neurodevelopmental and epilepsy phenotypes, although there is not sufficient evidence to confirm causality to date." (PMID 35606653, 2022).
medulloblastoma (2 papers, 2019 to 2022). A malignant, invasive embryonal neoplasm arising from the cerebellum. "Retroviral vector assays have been used to validate Eras, Lhx1, Ccrk, and Akt as mediators of medulloblastoma dissemination/metastasis in vivo." (PMID 31338332, 2019).
Müllerian aplasia (2 papers, 2013 to 2020). "We report here the results of genetic studies on Müllerian aplasia, namely, results of TBX6 and LHX1 mutation screening in 112 MA patients and CNV analysis in a subset of them." (PMID 23954021, 2013).
uterine corpus endometrial carcinoma (2 papers, 2022 to 2026). A endometrial carcinoma (disease) that involves the body of uterus. "Further, LHX1 expression correlated with poor overall survival in uterine corpus endometrial carcinoma cells and tissue within the Cancer Genome Atlas." (PMID 40693358, 2026).
autism spectrum disorder (1 paper, 2024). A spectrum of developmental disorders that includes autism, and Asperger syndrome. "LHX1 has been proposed as a candidate for neurodevelopmental findings and autism spectrum disorder, as well as in the microduplication syndrome." (PMID 39766333, 2024).
DiGeorge syndrome (1 paper, 2016). "Various promising CNVs have been reported located at 1q21.1 (RBM8A), 16p11.2 (TBX6), 17q12 (LHX1, HNF1B), as well as 22q11 associated with DiGeorge syndrome." (PMID 28003020, 2016).
embryonal carcinoma (1 paper, 2015). A non-seminomatous malignant germ cell tumor characterized by the presence of large germ cells with abundant cytoplasm resembling epithelial cells, geographic necrosis, high mitotic activity, and pseudoglandular and pseudopapillary structures formation. "DMSO-treated P19CL6 embryonal carcinoma cells transiently adopt a mesendodermal-like state, as judged by robust coexpression of Lhx1, Eomes, T, Foxa2, and Cxcr4." (PMID 26494787, 2015).
esophageal squamous cell carcinoma (1 paper, 2025). Esophageal squamous cell carcinoma (ESCC) is a type of esophageal carcinoma (EC) that can affect any part of the esophagus, but is usually located in the upper or middle third. "This study reveals that hypermethylation of under‐methylated regions (UMRs) within gene bodies is involved in the activation of oncogenic homeobox genes, particularly NKX2‐5 and LHX1, in esophageal squamous cell carcinoma (ESCC)." (PMID 40307990, 2025).
kidney cancer (1 paper, 2019). Primary or metastatic malignant neoplasm involving the kidney. "They showed LHX1 gene was re-expressed in kidney cancer and it is expressed in large quantities in kidney cancer cells, whereas in the normal kidney cells, it appears with a low expression level." (PMID 31908740, 2019).
membranous nephropathy (1 paper, 2012). "The significance of LHX1 in human disease remains an open question and it will be interesting to observe if eventually a connection between alterations of LHX1 and cases of membranous nephropathy such as ours can be demonstrated." (PMID 22583611, 2012).
pancreatic adenocarcinoma (1 paper, 2017). "We also observed differential methylation of RMRM (reprimo), CLDN5, LHX1, NTPX2, SPARC and ST14, which are already reported as aberrantly methylated genes in pancreatic adenocarcinoma." (PMID 28423671, 2017).
pheochromocytoma (1 paper, 2022). "Immunoreactivity to classic neuroendocrine markers such as CgA and synaptophysin is almost always present, and second-generation neuroendocrine markers ISL LIM Homeobox 1 (ISL1) and INSM1 have also been found as reliable markers of an adrenal medullary origin in pheochromocytoma." (PMID 35205664, 2022).
renal agenesis (1 paper, 2022). Renal agenesis (RA) is a form of renal tract malformation characterized by the complete absence of development of one or both kidneys (unilateral RA or bilateral RA respectively), accompanied by absent ureter(s). "LHX1 has been associated with MRKH type II and unilateral renal agenesis." (PMID 35883945, 2022).
seminoma (1 paper, 2026). A radiosensitive malignant germ cell tumor found in the testis (especially undescended), and extragonadal sites (anterior mediastinum and pineal gland). "A striking difference between area 1 and area 2 of the seminoma tumour specimen was the higher levels of transcription factor LHX1 and the tyrosine kinase receptor KIT in area 1 ROIs." (PMID 40693358, 2026). "LHX1 function in seminoma has not been studied, however, it is a marker of the earliest undifferentiated spermatogonial stem cells in the developing mouse testis." (PMID 40693358, 2026).
thyroid carcinomas (1 paper, 2024). "Metastasis to the lymph nodes from thyroid carcinomas has been demonstrated to be influenced by LHX1 upregulation." (PMID 38886487, 2024).
cancer (13 papers, 2014 to 2026). A tumor composed of atypical neoplastic, often pleomorphic cells that invade other tissues. "Most of these genes which may be affected due to HHV6a genomic insertions at or near the genes except for LHX1 were found to be significantly associated with different cancers (p-value = 8.54E–04)." (PMID 28410234, 2017). "This included the lncRNA/coding pair, PCAT6/KDM5B, and the coding/lncRNA pair, LHX1/LHX1-DT, which functions in malignant tumor cell growth." (PMID 37684517, 2023). "Among these, we identify a number of known cancer genes (i.e., FOXL2, RUNX1T1), transcription factors (i.e., MEIS2), as well as LHX1 and PAX6 (which are also recurrently affected by mutations)." (PMID 33741928, 2021). "LHX1 ChIP-seq data in differentiated P19 carcinoma cells shows a low confidence peak ∼1k bp upstream of the Foxd4 transcriptional start site (TSS)." (PMID 35178396, 2021). "Existing documents have shown the inappropriate expression of LHX1 in cancers that leads to the increased transcription, growth, and proliferation, as well as inhibition of cancer cell apoptosis 17,41." (PMID 31908740, 2019). "The LHX1 expression has been reported in human cancers such as ovarian cancer, kidney carcinoma, leukemia cells, and epithelial cells." (PMID 31908740, 2019). "The results of DNA samples from 40 cancer and 25 normal lung tissues showed a good diagnostic potential of selected RCGY sites in regulatory regions of MYF6, SIX6, RXRG, LHX1, RASSF1A and TERT genes with relatively high sensitivity (80.0 %) and specificity (88.0 %) of LC detection in tumor DNA." (PMID 31526458, 2019). "In addition, three loci (BC008699, SLC38A4 and LHX1) showed low frequencies of the methylation levels, similar to those observed in cancer tissue." (PMID 24490656, 2014). "Depletion of LHX1 restored STING-dependent SASP and impaired cancer stem cell self-renewal." (PMID 41608636, 2026). "However, the potential role of LHX1 was only suggested with the trend of dysregulation in cancer, but not yet by the functional assays in normal and oncogenic circumstance." (PMID 40183093, 2025).
tumor (11 papers, 2017 to 2026). "In UCEC patients, the LHX1 expression level was also positively correlated with the depth of tumor invasion." (PMID 36116266, 2022). "This is consistent with prior evidence, indicating that LHX1 can be regarded as a tumor cell marker." (PMID 36116266, 2022). "The following marker genes were differentially expressed in the triphasic tumours relative to the blastemal tumours: PA (LHX1), RV/CSB/SSB (BMP2, CDH6, JAG1, PAPSS2), ePT and/or imHL (CIDEB, CLIC6, UNC5CL, VDR), and early DT/imHL (KCNJ1)." (PMID 29040332, 2017). "Additionally, these findings further validate that simultaneous inhibition of both UHRF1 and DNMTs exhibits anti‐tumor activity by effectively suppressing the expression of NKX2‐5/LHX1." (PMID 40307990, 2025). "Our results demonstrated that combined treatment with NSC232003 and SGI‐1027 led to a more pronounced downregulation of NKX2‐5/LHX1 expression and superior tumor growth inhibition than either inhibitor alone, highlighting the potential of this combinatorial therapeutic approach for ESCC management." (PMID 40307990, 2025). "In this study, we employed human and mouse-derived HNSCC cell lines, xenograft models, and clinical samples to assess the functional relevance of LHX1 in regulating SASP and tumor progression." (PMID 41608636, 2026). "Here, we identify LIM homeobox 1 (LHX1) as a key transcriptional suppressor of STING, whose downregulation enables evasion of SASP-mediated tumor surveillance." (PMID 41608636, 2026). "We used CCK‐8 assays, colony formation studies, and tumor transplantation models to quantitatively assess the impacts of NKX2‐5 and LHX1 on ESCC cell proliferation." (PMID 40307990, 2025). "Our findings revealed that silencing NKX2‐5 or LHX1 significantly inhibited ESCC cell proliferation, colony formation, and tumor growth." (PMID 40307990, 2025). "This intricate interplay forms a positive transcriptional feedback loop between NKX2‐5/LHX1 and UHRF1, thus promoting the overexpression of all three genes and ultimately facilitating tumor growth." (PMID 40307990, 2025). "Notably, two of these genes, NKX2‐5 and LHX1, were found to play pivotal roles in the oncogenic transformation of normal esophageal epithelial cells and ESCC tumor growth." (PMID 40307990, 2025). "Notably, concurrent inhibition of UHRF1 and DNMTs impedes tumor growth by suppressing NKX2‐5 and LHX1 expression." (PMID 40307990, 2025).
neurodevelopmental disorder (2 papers, 2020 to 2021). A behavioral and cognitive disorder with onset during the developmental period that involves impaired or aberrant development of intellectual, motor, or social functions. "This suggested that there might be other protein-coding genes at 17q12 that contributed for the neurodevelopmental disorder, such as LHX1 and ACACA, and were referred to as the genes involved in the neurodevelopmental syndrome." (PMID 32429945, 2020). "LHX1 is involved in neuronal differentiation, axon migration, and in cerebellum development, thus it may concur with ASD and with other neurodevelopmental disorders described in these recurrent syndromes." (PMID 34828266, 2021).
kidney (1 paper, 2024). "Gene Ontology Overview of the deleted genes showed both HNF1B deletions and LHX1 deletions have significant impacts on structural or functional kidney dysfunctions and malformations of the reproductive system." (PMID 39221224, 2024).
renal disease (1 paper, 2024). "Besides the well-recognized role of HNF1B, among other genes encompassed in the genomic region, LHX1 has been proposed as a possible modifier for earlier onset renal disease." (PMID 39766333, 2024).
LHX1 also shares sentences with these, for which no sentence is quoted: Mayer-Rokitansky-Küster-Hauser (MRKH) syndrome (3 papers); Nephroblastoma (2); acute lymphoblastic leukemia (1); amyotrophic lateral sclerosis (1); angiomyolipoma (1); autism (1); Autosomal dominant tubulointerstitial kidney diseases (1); cervical cancer (1); chronic leukemia (1); chronic myeloid leukemia (1); diabetes mellitus (1); E. coli infection (1); follicular lymphoma (1); head and neck squamous cell carcinoma (1); hepatocellular carcinoma (1); Hip dysplasia (1); leukemia (1); lymph node metastasis (1); Macrocephaly (1); maturity-onset diabetes of the young type 5 (1); mental retardation (1); metabolic disorders (1); microcephaly (1); Micrognathia (1); neuroendocrine carcinoma (1); Obesity (1); ocular hypertelorism (1); ovarian carcinoma (1); pancreatic cancer (1); PEComas (1).
A further 4 diseases each share a sentence with LHX1 in 1 paper.